USP41P (ubiquitin specific peptidase 41, pseudogene)
Synonyms: USP18B; USP41
Gene: Transcribed unprocessed pseudogene on chromosome 22 (20,363,621 to 20,377,251, reverse strand). Ensembl gene ENSG00000161133.
Genetic constraint (gnomAD): Loss-of-function variants: 20 observed, 37.12 expected, observed/expected ratio (o/e) 0.54, 90% interval 0.38 to 0.78. The upper end of that interval is the gene's LOEUF score, 0.78, which puts it in group 3 of 6, group 1 being the genes least tolerant of losing a copy. Missense variants: 256 observed, 321.96 expected, observed/expected ratio (o/e) 0.8, 90% interval 0.72 to 0.88. Synonymous variants: 98 observed, 121.32 expected, observed/expected ratio (o/e) 0.81, 90% interval 0.69 to 0.95.
Diseases named in the same sentence as USP41P in open-access papers:
USP41P is named in the same sentence as 8 diseases in open-access papers, as found by Europe PMC text mining. Sharing a sentence is not in itself a finding about the gene and the disease.
USP41P shares sentences with these, for which no sentence is quoted: breast carcinoma (5 papers); lung carcinoma (5); cancer (3); Tumor (3); lung adenocarcinoma (2); osteosarcoma (2); Breast Tumor (1); invasive breast carcinoma (1).